ORC6 (origin recognition complex subunit 6)
Diseases named in the same sentence as ORC6 in open-access papers (continued):
Sharing a sentence is not in itself a finding about the gene and the disease.
glioma (continued). "Together, RBPJ-driven ORC6 overexpression promotes glioma cell growth, underscoring its significance as a promising therapeutic target." (PMID 38971772, 2024). "Alternatively, we utilized a lentiviral CRISPR/Cas9-ORC6-KO construct to establish ORC6 knockout (KO) in P1 glioma cells, termed “koORC6”." (PMID 38971772, 2024). "Altogether, RBPJ-driven ORC6 overexpression promotes glioma cell growth, underscoring its significance as a promising therapeutic target." (PMID 38971772, 2024). "Significantly, our results discovered strengthened binding between the RBPJ protein and the ORC6 promoter region across various glioma tissues and also in primary/immortalized glioma cells." (PMID 38971772, 2024). "The results revealed a significant increase in ORC6 mRNA expression within the tested glioma cells, compared to that observed in primary human astrocytes (“Astrocytes1/2”)." (PMID 38971772, 2024). "In primary and immortalized (A172) glioma cells, depleting ORC6 using specific shRNA or Cas9-sgRNA knockout (KO) significantly decreased cell viability and proliferation, disrupted cell cycle progression and mobility, and triggered apoptosis." (PMID 38971772, 2024). "Through the bioinformatics analyses, we found a significant increase in ORC6 expression within human glioma tissues, correlating with poorer overall survival, higher tumor grade, and wild-type isocitrate dehydrogenase status." (PMID 38971772, 2024). "Next, the assessment of ORC6 expression was conducted on local human glioma tissues, consisting of twenty (n = 20) HGG tissues (“T”) paired with their corresponding adjacent normal brain tissues (“N”)." (PMID 38971772, 2024). "These collective findings strongly suggest that ORC6 KO impeded the growth of intracranial P1 glioma xenografts in nude mice." (PMID 38971772, 2024). "ORC6 depletion, inhibited proliferation, decreased expression of Cyclin A2/B2/TOP2A, and increased apoptosis were detected within these ORC6 KO intracranial glioma xenografts." (PMID 38971772, 2024). "Analysis from the Chinese Glioma Genome Atlas (CGGA) database underscores that glioma patients exhibiting heightened ORC6 expression (n = 307) tend to have lower survival rates than those with low ORC6 expression (n = 307) (P < 0.001)." (PMID 38971772, 2024). "In contrast, in P1 glioma cells overexpressing ORC6, “oeORC6-Slc1” and “oeORC6-Slc2,” there was a significant elevation observed in both mRNA and protein expression levels of Cyclin A2, Cyclin B2, and TOP2A." (PMID 38971772, 2024). "Cell cycle analyses revealed an observed accumulation of cells in the G1 phase and a concurrent decrease in the S phase after silencing or knocking out of ORC6 in P1 glioma cells." (PMID 38971772, 2024). "Conversely, elevating ORC6 levels via a lentiviral construct intensified malignant behaviors of glioma cells." (PMID 38971772, 2024). "A significantly higher level of ORC6 mRNA expression in glioma tissues (“Tumor,” n = 701) was detected as compared to the normal tissues (“Normal,” n = 5)." (PMID 38971772, 2024). "Considering the increase in both mRNA and protein expression of ORC6 within glioma tissues and cells, we next tested the potential involvement of a transcriptional mechanism in driving this upregulation." (PMID 38971772, 2024). "Here, the observed downregulation in both mRNA and protein levels of Cyclin A2 and Cyclin B2 upon silencing or knocking out ORC6, as well as the increased cyclins expression upon ORC6 overexpression in primary human glioma cells." (PMID 38971772, 2024). "Our study explored the potential mechanism responsible for the increased expression of ORC6 in human glioma, highlighting the pivotal role of RBPJ as a crucial transcription factor." (PMID 38971772, 2024). "The mRNA and protein expression of ORC6 robustly decreased in the koORC6 intracranial P1 glioma xenograft tissues." (PMID 38971772, 2024).
glioma (continued). "Subsequent analysis revealed a significant increase in the expression of ORC6 mRNA and protein in the oeORC6-expressing P1 glioma cells, where the expression of ORC2 mRNA and protein remained unaltered." (PMID 38971772, 2024). "Conversely, enhancing ORC6 expression via a lentiviral construct augmented malignant behaviors in human glioma cells." (PMID 38971772, 2024). "Expression of ORC6 is upregulated in the majority of cancer types and is associated with poor patient prognosis, notably in cases of LIHC and gliomas." (PMID 37901236, 2023). "MiR-1-3p inhibits the progression of Glioma by regulating ORC6 expression." (PMID 39951205, 2025). "Cell viability, tested via CCK-8 assays, was also decreased in ORC6-depleted P1 glioma cells." (PMID 38971772, 2024). "Additionally, ORC6 overexpression is detected in glioma tissues obtained from locally-treated patients and across various primary/established glioma cells." (PMID 38971772, 2024). "The levels of ORC6 mRNA exhibited a significant increase in local glioma tissues." (PMID 38971772, 2024). "Subsequently, we investigated whether silencing of ORC6 produced similar effects in other glioma cells, encompassing primary cells derived from other patients (P2 and P3) and immortalized A172 cells." (PMID 38971772, 2024). "When compared to the control P1 glioma cells treated with lentiviral scramble control shRNA plus the CRISPR/Cas9 control construct (“shC+Cas9-C”), the expression of ORC6 mRNA and protein was significantly reduced in shORC6-s1/s2 P1 glioma cells and koORC6 P1 glioma cells." (PMID 38971772, 2024). "Our data strongly supported that ORC6 regulates the expression of TOP2A within glioma cells." (PMID 38971772, 2024). "The receiver operating characteristic (ROC) curve analysis for ORC6 expression yielded an area under the curve (AUC) of 0.916, suggesting that ORC6 overexpression can be a robust biomarker for diagnosing between normal and glioma tissues." (PMID 38971772, 2024). "Moreover, ORC6 overexpression is evident in glioma tissues derived from locally-treated patients and in a spectrum of primary and established glioma cells." (PMID 38971772, 2024). "The in vitro migration and invasion of P1 glioma cells were accelerated upon ORC6 overexpression." (PMID 38971772, 2024). "Furthermore, among four selected HGG patients (Patient-1# to Patient-4#), ORC6 protein expression demonstrated a significant elevation in the glioma tissues." (PMID 38971772, 2024). "Furthermore, within HGG tissues (grade III–IV), ORC6 expression is significantly higher compared to that in grade II LGG glioma tissues." (PMID 38971772, 2024). "TOP2A downregulation was also detected in ORC6 KO intracranial glioma xenograft tissue." (PMID 38971772, 2024). "Importantly, overexpression of ORC6 is associated with wild-type IDH status within glioma tissues (P = 0.014), while IDH mutant glioma tissues exhibit comparatively lower ORC6 expression." (PMID 38971772, 2024). "Thus, TCGA database reveals that ORC6 is significantly elevated in glioma and correlates with poor prognosis and various clinical parameters of glioma." (PMID 38971772, 2024). "Additionally, significantly enhanced binding between the RBPJ protein and the proposed ORC6 promoter region was detected in glioma tissues and cells." (PMID 38971772, 2024). "In light of bioinformatic studies highlighting the close association between ORC6 and key oncogenic genes, including Cyclin A2, Cyclin B2, and TOP2A in GBM, our study explored the potential role of ORC6 in regulating their expression in glioma cells." (PMID 38971772, 2024). "Additionally, genetic silencing or KO of ORC6 impeded the in vitro migration and invasion of P1 glioma cells, as assessed through the “Transwell” and “Matrigel Transwell” assays, respectively." (PMID 38971772, 2024).
glioma (continued). "Depletion of ORC6 using specific shRNA or Cas9-sgRNA KO significantly reduced cell viability and proliferation while disrupting cell cycle progression and mobility, eventually inducing apoptosis in primary and immortalized (A172) glioma cells." (PMID 38971772, 2024). "Moreover, the upregulation of ORC6 protein was evident in both primary and immortalized glioma cells." (PMID 38971772, 2024). "Additionally, the expression of ORC6 in high-grade glioma (HGG) significantly exceeds that in low-grade glioma (LGG) tissues." (PMID 38971772, 2024). "Additionally, the levels of cleaved forms of caspase-3 (Clvd-caspase-3) and caspase-9 were elevated in ORC6-silenced/-KO P1 glioma cells." (PMID 38971772, 2024). "Subsequent experiments were carried out to determine whether ORC6 was upregulated in various human glioma cells, including primary human glioma cells (“P1–P3,” derived from three patients) and immortalized A172 cells." (PMID 38971772, 2024). "Similarly, the increase in cyclin A2/B2 mRNA levels in glioma cells with ORC6 overexpression might also be attributed to an expanded S phase population due to such overexpression." (PMID 38971772, 2024). "Therefore, enhanced binding between RBPJ-ORC6 promoter might represent a crucial mechanism contributing to the increased expression of ORC6 in human glioma." (PMID 38971772, 2024). "Utilizing “shORC6-s1” and “shORC6-s2” to knock down ORC6 or employing the CRISPR/Cas9 method to KO ORC6 led to increased caspase-3 and caspase-9 activities within P1 glioma cells." (PMID 38971772, 2024). "Here in P1 glioma cells, experimentally reducing RBPJ expression using lentiviral shRNAs resulted in decreased ORC6 expression at both the mRNA and protein levels." (PMID 38971772, 2024). "Significantly, ChIP assay results demonstrated a significant increase in the binding between the RBPJ protein and the presumed ORC6 promoter region’s binding cites (GCTGGGAAGG, from JASPAR database) within glioma tissues obtained from local patients." (PMID 38971772, 2024). "ORC6 emerged as a crucial regulator for the expression of key oncogenic genes, including Cyclin A2, Cyclin B2, and DNA topoisomerase II (TOP2A), within glioma cells." (PMID 38971772, 2024). "Importantly, ORC6 overexpression showed significant associations with various clinical parameters, including age, WHO grading, pathological classification, and ORC6 expression within glioma tissues is significantly elevated in deceased patients compared to those who are still alive." (PMID 38971772, 2024). "To clarify the expression and function of ORC6 in hepatocellular carcinoma (LIHC) and glioma, we conducted in vitro experiments." (PMID 37901236, 2023). "Inhibiting ORC6 expression suppressed the proliferative and migratory abilities of LIHC and glioma cells." (PMID 37901236, 2023). "As shown, the number of ORC6 transcripts in glioma tissues (n = 454) was significantly higher than that in normal (n = 21) brain tissues." (PMID 38971772, 2024). "In order to study the potential role of ORC6 in glioma cell growth in vivo, the P1 glioma cells expressing the CRISPR/Cas9-ORC6-KO construct (“koORC6”) or the Cas9-C control (“Cas9-C”) were injected intracranially into the brains of nude mice (according to the previously-described protocols)." (PMID 38971772, 2024). "In contrast to P1 glioma cells with scramble control shRNA (“shC”), cells with shRBPJ displayed a remarkable decrease in RBPJ mRNA and protein expression, accompanied by a significant reduction in ORC6 mRNA and protein expression." (PMID 38971772, 2024). "Furthermore, in gliomas, which include GBM and LGG, ORC6 expression was negatively correlated with the abundance of infiltrating immune cells, including Tem CD8, Tcm CD4, Tfh, Th1, Th17, Act B, lmm B, NK, MDSC, NKT, Act DC, pDC, iDC, macrophage, eosinophil, mast, monocyte, and neutrophil cells." (PMID 37901236, 2023).
clear cell renal cell carcinoma (3 papers, 2022 to 2024). "ORC6 overexpression significantly correlated with decreased overall survival in clear cell renal cell carcinoma." (PMID 38971772, 2024).
hepatocellular carcinoma (3 papers, 2021 to 2023). A malignant tumor that arises from hepatocytes. "Moreover, ORC6 promotes proliferation, migration, and invasion of hepatocellular carcinoma cells." (PMID 36205357, 2023).
breast tumor (2 papers, 2019 to 2022). "Just like the CST2, GJB2, UBE2T, NUF2 and ORC6 also showed the same high expression level in breast tumors." (PMID 31182966, 2019). "Interestingly, both SHCBP1 and ORC6 also showed elevated expression in breast tumor samples compared to control samples in TCGA studies (FC = 7.42 and 5.48, respectively)." (PMID 35886011, 2022).
head and neck cancer (2 papers, 2023). A primary or metastatic malignant neoplasm affecting the head and neck. "Regarding its protein expression in tumors, we observed that ORC6 was moderately/highly expressed in 100% of head and neck cancer (3/3) and testicular cancer (11/11) tissues and was moderately/highly expressed in 54.5% (6/11) of liver cancer tissues." (PMID 37901236, 2023). "The ORC6 protein level was highest in head and neck cancer and testis cancer but lowest in renal cancer." (PMID 36978046, 2023).
lung adenocarcinoma (2 papers, 2021 to 2024). A carcinoma that arises from the lung and is characterized by the presence of malignant glandular epithelial cells. "Analysis of the TCGA-lung adenocarcinoma database revealed a notable increase in ORC6 expression in lung adenocarcinoma tissues, correlating with reduced overall survival, advanced disease stages, and other key clinical parameters." (PMID 39349930, 2024).
acute lymphoblastic leukemia (1 paper, 2023). Leukemia with an acute onset, characterized by the presence of lymphoblasts in the bone marrow and the peripheral blood. "According to the information about distinct cell lines extracted from the CCLE database, the highest ORC6 expression levels were found in ALL (acute lymphoblastic leukemia), normal breast (NB), and DLBC cells." (PMID 36978046, 2023).
ciliopathy (1 paper, 2021). A genetic disorder of the cellular cilia or the cilia anchoring structures, the basal bodies, or of ciliary function. "An intriguing connection between MGS and ciliopathy is based on the observation that depletion of ORC1, ORC4, ORC6, CDT1 and CDC6 leads to reduced primary cilia formation." (PMID 33477564, 2021). "When fibroblasts were depleted for ORC1, ORC4, ORC6, CDT1 and CDC6, primary cilia formation was impaired, suggesting that MGS symptoms might constitute a ciliopathy." (PMID 33477564, 2021).
Jeune syndrome (1 paper, 2022). Jeune syndrome, also called asphyxiating thoracic dystrophy, is a short-rib dysplasia characterized by a narrow thorax, short limbs and radiological skeletal abnormalities including "trident" aspect of the acetabula and metaphyseal changes.
liver neoplasm (1 paper, 2025). Tumors or cancers of the LIVER. "The ‘liver neoplasms’ CTD over-representation could be attributed to cell cycle-related pathway enrichment and corresponding genes (cell cycle: PDS5A, ORC6, RAD21, ZBTB17; Thyroid cancer: CTNNB1, RET) identified from our CRIPSR screens." (PMID 41446233, 2025).
lung carcinoma (1 paper, 2023). "The lung cancer dataset showed that the DNA alteration percentages of the ORC complex were 1.9% (ORC1), 1.7% (ORC2), 1.5% (ORC3), 1.2% (ORC4), 2.2% (ORC5), and 1.4% (ORC6)." (PMID 36205357, 2023).
medulloblastoma (1 paper, 2017). A malignant, invasive embryonal neoplasm arising from the cerebellum. "Interestingly, here we found that Gmnn levels in human medulloblastomas did not correlate with tumor subtype, histology, or other criteria, but did correlate with elevation of cell cycle related genes, including pre-RC proteins (MCM6, ORC1, and ORC6)." (PMID 29234490, 2017).
melanoma (1 paper, 2023). A malignant, usually aggressive tumor composed of atypical, neoplastic melanocytes. "Furthermore, we observed that in the melanoma immunotherapy cohort, the high ORC6 expression group had prolonged survival after immunotherapy (p=0.027)." (PMID 37901236, 2023).
osteosarcoma (1 paper, 2022). A usually aggressive malignant bone-forming mesenchymal neoplasm, predominantly affecting adolescents and young adults. "IGFBP5 has been identified as a hub gene in osteosarcoma along with origin recognition complex subunit 6 (ORC6), minichromosome maintenance 10 replication initiation factor (MCM10), MET proto-oncogene, receptor tyrosine kinase (MET) and centromere protein F (CENPF)." (PMID 36465383, 2022).
prostate adenocarcinoma (1 paper, 2023). "Our results prove that ORC6 might be a promising prognostic biomarker and an immunotherapeutic target for multiple cancers, especially prostate adenocarcinoma." (PMID 36978046, 2023). "Furthermore, to validate the correlation between ORC6 expression and Treg cell infiltration, IHC staining of FOXP3, which serves as a lineage specification factor of Treg cells, was performed in tumor samples from 19 patients with prostate adenocarcinoma." (PMID 36978046, 2023).
urothelial carcinoma (1 paper, 2023). A malignant neoplasm derived from the transitional epithelium of the urinary tract (urinary bladder, ureter, urethra, or renal pelvis). "Notably, in the advanced urothelial carcinoma cohort with immunotherapy, the response group had significantly higher ORC6 expression (p=0.00099)." (PMID 37901236, 2023).